INS (insulin)
Diseases named in the same sentence as INS in open-access papers (continued):
Sharing a sentence is not in itself a finding about the gene and the disease.
Insulin resistance (continued). "Elevated plasma insulin levels but unaltered glucose levels suggest that the HFD-Asb4−/− dams developed insulin resistance." (PMID 36768469, 2023). "While L. digitata reduced glucose, increasing in parallel IGF-1, both insulin and insulin resistance index were unaffected by diets, suggesting the maintenance of glycaemia homeostasis." (PMID 37087466, 2023). "In contrast, LTI treatment reduced glucose uptake by 51.6% compared to that with insulin alone, which indicated the presence of insulin resistance, while Fuc treatment increased the reduction of glucose uptake to levels comparable to those untreated with LTI." (PMID 36771210, 2023). "The accumulation of lipids in non-adipose tissues is a distinguished event in various models of insulin resistance, resulting in both direct (via reactive lipids) and indirect (via mitochondrial ROS emission) impairments in peripheral insulin signalling." (PMID 37153211, 2023). "This hormone also affects the development of peripheral insulin resistance by weakening the effect of insulin on insulin-sensitive cells." (PMID 37239168, 2023). "Insulin resistance (IR) refers to the decreased responsiveness of the target cells of the skeletal muscle to insulin and to impaired glucose metabolism in cells throughout the body,it further induces the development of sarcopenia." (PMID 36918975, 2023). "The only other statistically significant difference measured post GHT, was that of fasting insulin levels which were higher after GH treatment indicating early post-therapy insulin resistance induced by GH." (PMID 37705005, 2023). "Since type 2 diabetes is also characterized by insulin resistance, the changes of key factors of insulin signaling with different diets should be further studied." (PMID 36986243, 2023). "Insulin resistance develops due to increased levels of cytokines and hormones that inhibit insulin signaling." (PMID 37799768, 2023). "Key characteristics of T2D are insulin resistance and insufficient insulin production from beta-cells, leading to hyperglycemia." (PMID 36901964, 2023). "The results showed that 1-DNJ improved insulin resistance, increased insulin sensitivity and lowered blood glucose, all in a dose-dependent manner." (PMID 37089923, 2023). "HC also had similar metabolic effects in male and female mice resulting in classical increases of circulating insulin indicative of insulin resistance." (PMID 37650517, 2023). "Under insulin resistance, insulin signaling pathways undergo various alterations, resulting in decreased insulin activity." (PMID 37965322, 2023). "The increasing plasma insulin and (log2)insulin:glucose ratio, higher leptin and low adiponectin are suggestive of insulin resistance in the feedlot finishing phase." (PMID 37041373, 2023). "In both in vitro models, we established a condition of insulin resistance by prolonged treatment with high insulin concentrations." (PMID 36901549, 2023). "Since insulin resistance is the result of decreased insulin sensitivity in metabolic tissues such as skeletal muscle, adipose tissue and liver, we studied the activation of the PI3K/Akt pathway in these tissues in response to insulin." (PMID 37239868, 2023). "This insulin resistance, along with compensatory high insulin levels, can contribute to enhanced bone mineral density." (PMID 37782659, 2023). "NS attenuates insulin resistance, enhances insulin signaling, suppresses cyclooxygenase-2, upregulates insulin-like growth factor-1, and prevents endothelial dysfunction in DM." (PMID 37818339, 2023). "It was shown that both insulin sensitivity and β-cell function are significantly decreased with a 0.6% increase in glycohemoglobin and that insulin resistance can be found by detecting HbA1C." (PMID 37268889, 2023). "It does not seem that obesity significantly affects the basic parameters of the carbohydrate metabolism of a pregnant woman, in particular the level of glucose, serum insulin, and the insulin resistance index (HOMA-IR)." (PMID 37432262, 2023).
Insulin resistance (continued). "In AD and related disorders, insulin resistance is due to impaired insulin signaling, so AD is denominated as brain diabetes or “Type 3 Diabetes”." (PMID 36902167, 2023). "Insulin resistance (IR) is a condition in which more insulin is required to reach a certain plasma glucose concentration than in insulin-sensitive situations." (PMID 36678311, 2023). "First, it can delay insulin resistance or increase insulin secretion, and intervene before kidney injury occurs." (PMID 38111708, 2023). "Insulin resistance is defined as impaired signal transduction and biological actions in response to insulin stimulation, resulting in a decrease in the ability of insulin to increase glucose uptake and utilization." (PMID 36677050, 2023). "The contribution of obesity to insulin resistance is beyond the impairment of insulin signaling but involves the interplays of various metabolic pathways and essential nutrients and metabolites." (PMID 37152942, 2023). "Insulin resistance is a condition wherein the pancreas must secrete an elevated amount of insulin compared to the usual levels required to maintain normal blood glucose levels." (PMID 38054122, 2023). "Lowering the endogen insulin levels and insulin resistance appears to be a target to improve fertility and pregnancy outcomes in those women." (PMID 36676074, 2023). "The pathophysiology of T2DM is characterized by a decrease in insulin-regulated glucose metabolism (i.e., insulin resistance) accompanied by a decrease (or relative decrease) in insulin secretion due to defective islet b-cell function." (PMID 38137191, 2023). "The physiological function of FGF-21 is mainly involved in glycolipid metabolism and the metabolic regulation of insulin, body weight reduction and insulin resistance improvement." (PMID 37070097, 2023). "This biased Type-1 immune response aggravates insulin resistance through stress-activated kinases that target intermediates in the insulin-signalling pathway." (PMID 37495576, 2023). "Cluster 3 was “Medium-Risk”, included 134 inpatients (accounting for 5.91%), characterized by the worst blood sugar control, the insulin sensitivity was the worst, and the degree of insulin resistance (IR) was also the most serious among the four groups." (PMID 37929026, 2023). "According to a recent study, SV attenuated insulin resistance in rats fed a high-fat diet by activating the insulin signaling pathway in their muscles." (PMID 37488560, 2023). "Insulin-mediated inhibition of lipolysis in adipose tissue is weakened by insulin resistance, which leads to a significantly increased release of FFAs and glycerol into the bloodstream." (PMID 36977005, 2023). "Increased fat and elevated circulating amino acids in particular have been found to contribute to nutrient overload, which in turn increases mTOR activation which can result in insulin resistance in peripheral insulin-responsive tissues." (PMID 36826001, 2023). "CNS insulin resistance appears to negatively influence whole brain insulin transport and overall regional uptake more greatly in females." (PMID 37076875, 2023). "Consequentially, even in presence of insulin resistance, when insulin signaling is impaired, E4orf1 is able to promote glucose disposal and reduce response of endogenous insulin to glucose load." (PMID 37573386, 2023). "Insulin resistance results from a defect in insulin action, including insulin-mediated glucose transport and its signaling pathway." (PMID 37509682, 2023). "In the presence of insulin resistance, insulin sensitivity of peripheral tissues decreases and hyperinsulinism develops accordingly." (PMID 35765946, 2023). "The nutrient overload model of insulin resistance suggesting elevated mTORC1 signaling leads to insulin resistance via feedback inhibition of insulin/PI3K/AKT signaling from S6K." (PMID 38066609, 2023).
Insulin resistance (continued). "The long-standing activation of β-cells leads to insulin resistance and later to β-cell apoptosis, decreased insulin biosynthesis, and subsequently reduced insulin secretion." (PMID 37894792, 2023). "GLUT4 is the main effector of the insulin signal, and the insulin resistance, characteristic of T2DM, is due to the deteriorated trafficking of GLUT4 into the cell membrane, which contributes to insulin resistance in muscle and adipocytes." (PMID 37047055, 2023). "Insulin resistance, the defective responsiveness of the peripheral tissues to insulin, results in hyperglycemia and leads to type 2 diabetes (T2DM) and its complications, such as cardiovascular disease, retinopathy, and chronic kidney disease." (PMID 36834930, 2023). "The findings of this study suggest that beinaglutide is effective in reducing body weight, alleviating insulin resistance, and improving insulin sensitivity." (PMID 38125788, 2023). "After glucose intake, FPLD2 patients showed an excessive insulin response and revealed insulin resistance, as well as a decreased response of plasma glucose to exogenously administered insulin." (PMID 36899861, 2023). "Both ultradian factors and different sleep stages influence insulin secretion and insulin resistance." (PMID 39434962, 2023). "The accumulation of excessive fat produced and secreted adipocytokines, which interfered with insulin signaling pathways, resulting in the progression of insulin resistance and T2DM." (PMID 37426418, 2023). "The main pathophysiological disturbances in T2D are impaired insulin secretion and insulin resistance." (PMID 36398677, 2023). "A chronic imbalance between caloric intake and expenditure together with impaired micronutrient intake can lead to obesity and insulin resistance on one hand, and β-cell failure and defective insulin production on the other." (PMID 37432389, 2023). "Many previous studies have proved that RES can improve renal insulin signaling to ameliorate insulin resistance, and provide a neuroprotective and cardioprotective effect by targeting PI3K-AKT pathway." (PMID 37308949, 2023). "The serum vitamin D levels, lipid profiles, fasting blood glucose levels, hemoglobin A1c levels, fasting insulin levels, and insulin resistance (IR) were evaluated." (PMID 38013283, 2023). "Performing a KSEA now using these sites revealed that GSK3 was inactivated in response to insulin in control cells in our original phosphoproteomics study as expected, and remarkably, that this inactivation was attenuated across all insulin resistance models." (PMID 36808134, 2023). "MDA binds covalently to lipids and proteins and leads to the formation of cross-links, which disrupts the interaction between insulin and its receptors, reducing the number of insulin-binding sites and contributing to insulin resistance." (PMID 37686346, 2023). "In cases of insulin resistance, a clinical condition marked by reduced biological responsiveness to insulin at any given blood concentration, there is a noteworthy connection to CKD according to various epidemiologic studies." (PMID 38276262, 2023). "Prolonged exposure to high levels of insulin has been shown to lead to insulin resistance and, eventually, type 2 diabetes (T2D) development." (PMID 37375588, 2023). "Impaired insulin sensitivity and subsequent changes in glucose metabolism (as shown by the high prevalence of insulin resistance and glucose intolerance) are unquestionably acquired in chronic liver diseases like cirrhosis." (PMID 37255908, 2023). "Insulin resistance occurs when these tissues become less responsive to insulin, leading to impaired glucose uptake and metabolism, and resulting in hyperglycemia." (PMID 37240157, 2023). "For the purpose of normalization, insulin sensitivity was indicated by the index of insulin resistance (IR), calculated as the product of the blood concentrations of glucose and insulin." (PMID 36901928, 2023).
Insulin resistance (continued). "A plausible mechanism involves a decrease in oxidative stress, a process that can damage the insulin-producing beta cells and lead to impaired beta cell function and insulin resistance." (PMID 37299509, 2023). "ADPN and resistin can regulate insulin sensitivity and reduce glucose output and insulin resistance." (PMID 37569125, 2023). "Since the product of FFA times insulin reflects adipose insulin resistance, the conclusion is that adrenalectomy in these mice was associated with a 61.3% reduction in adipose insulin resistance (lipolysis)." (PMID 38260129, 2023). "In this study, we first found lower ZFYVE28 expression in obese patients with normal insulin sensitivity, while higher expression was observed in MetS patients with insulin resistance." (PMID 37884540, 2023). "The insulin resistance group and the control group differed significantly (p = 0.002) with respect to fasting insulin levels: in the insulin resistance and the control group, the corresponding values were 20.51 ± 14.33 ng/L and 3.13 ± 1.53 ng/L, respectively." (PMID 36771460, 2023). "These factors ultimately reduce the function and activity of β cells, leading to a significant decrease in insulin secretion and worsening insulin resistance, ultimately leading to the onset of ketosis." (PMID 38027130, 2023). "Serum insulin levels which were known to be elevated in early stages of insulin resistance and type 2 diabetes was measured in both the groups." (PMID 36873578, 2023). "Insulin resistance refers to the state of reduced sensitivity and responsiveness of the body to insulin, which has important pathophysiological significance in the development of obesity, T2DM, metabolic syndrome, cardiovascular and cerebrovascular diseases." (PMID 37964964, 2023). "Vitamin D alters insulin sensitivity in two main ways; regulating insulin receptor gene expression, which can be related to insulin resistance, and mediating calcium metabolism, thus increasing glucose transporter bioactivity." (PMID 37353689, 2023). "Analyses of mouse plasma lactate (F), plasma glucose (G), and insulin (H), homeostatic model of assessment of insulin resistance (HOMA-IR, I) after a 6 hr fast." (PMID 36722855, 2023). "Since A. muciniphila modulates obesity by regulating metabolism and energy homeostasis to improve insulin sensitivity and glucose homeostasis, low Verrucomicrobiota population possibly contributed to the insulin resistance reported for CST-KO mice." (PMID 37242791, 2023). "The therapeutic role of inositol has also been investigated for T2D, a disorder characterized by insulin resistance, altered insulin release, and excessive hepatic glucose production." (PMID 36826058, 2023). "It has been shown that hypertriglyceridemia was closely related to islet β-cell dysfunctions, including interfered β-cell maturation, suppressed β-cell proliferation, inhibited insulin secretion, and induced insulin resistance." (PMID 37497350, 2023). "In diabetic patients, insulin resistance promotes the progression of OA by impairing the protective and anti-inflammatory effects of insulin within the synovium." (PMID 38052778, 2023). "In insulin resistance, the body requires more insulin to maintain blood sugar levels, depriving brain neurons of sufficient energy support." (PMID 37740187, 2023). "STXBP4 phosphorylation is required for insulin-stimulated Glut4 translocation and glucose uptake, suggesting that defects in STXBP4 phosphorylation underlie insulin resistance." (PMID 37545519, 2023). "The findings also suggest that the risk of T2DM development is associated with a specific lipidomic profile which is characterized by lower peripheral insulin sensitivity and higher hepatic insulin resistance." (PMID 37537576, 2023). "Insulin resistance markers HOMA2-IR and HOMA2-%B were mostly associated to the same glycan structures as fasting insulin." (PMID 37079606, 2023).
Insulin resistance (continued). "It has been suggested that Il-6 and TNF-alpha are involved in the pathogenesis of insulin resistance and type 2 diabetes by inhibiting insulin receptor tyrosine phosphorylation and reducing insulin production in pancreatic beta cells." (PMID 37509592, 2023). "Insulin resistance in muscle and adipose tissue is defined by impaired insulin-stimulated translocation of GLUT4 to the PM and an associated reduction in glucose uptake." (PMID 37248992, 2023). "In T2D and obesity conditions where insulin resistance is manifested, impaired insulin activity increases endogenous hepatic glucose production and decreases glucose uptake, thereby leading to glycotoxicity in organs such as adipose tissues and muscle." (PMID 37755259, 2023). "The results indicate that combinational use of ARVs upregulates inflammasome activation and promotes insulin resistance through dysregulation of the IRS1/PI3K/AKT insulin signaling pathway." (PMID 37047241, 2023). "Chronic insulin exposure reduced peripheral insulin tolerance, which supports previous findings that insulin alone, from endogenous or exogenous sources, promotes insulin resistance." (PMID 38068958, 2023). "Insulin resistance hampers the uptake and utilization of glucose by skeletal muscles, contributing to a decrease in insulin sensitivity." (PMID 37576879, 2023). "PPARG is the first gene abnormally expressed due to induced insulin resistance, playing a crucial role in insulin signaling regulation and insulin sensitivity." (PMID 37475719, 2023). "Those agents improve insulin resistance in humans, specifically by boosting the disposal of insulin-stimulated glucose from skeletal muscle." (PMID 37408757, 2023). "The homeostasis model assessment (HOMA) of insulin resistance (IR) is a surrogate marker that estimates insulin resistance based on basal measurements of plasma insulin and glucose." (PMID 36468919, 2023). "In the event of rising insulin resistance, in order to maintain euglycemia, β cells of pancreatic islets attempt to compensate for insulin resistance by increasing insulin secretion." (PMID 37445466, 2023). "Insulin resistance became more severe with prolonged feeding, increasing the load of insulin secretion and reducing the required dose of STZ." (PMID 37723622, 2023). "So enhancing mitochondrial function also promote insulin sensitivity, and improve insulin resistance." (PMID 37337224, 2023). "We also found that sodium butyrate improved glucose metabolism by decreasing fasting serum glucose, insulin, and homeostasis assessment model insulin resistance ( HOMA‐IR) (p < 0.05)." (PMID 36382553, 2023). "In our study, in normal UA populations, the higher insulin level in Tibetans relative to Hans indicated possibly worsened insulin resistance in Tibetans." (PMID 38089618, 2023). "Glucocorticoids induce hyperglycemia by increasing insulin resistance and reducing insulin sensitivity." (PMID 38057700, 2023). "As TyG index is mainly a surrogate marker of insulin resistance, interventions aiming to enhance insulin sensitivity should be encouraged and tested in future trials." (PMID 38025208, 2023). "Chronic and mild inflammation can induce local or systemic insulin resistance (IR), which in turn induces high levels of insulin and IGF-1, thus stimulating abnormal hepatocyte proliferation." (PMID 37266440, 2023). "Insulin resistance refers to an impaired ability of insulin to lower blood glucose in target tissues at a normal plasma insulin level." (PMID 37960324, 2023). "Nonsense mutations in CD36 are also being associated with insulin resistance, familial type 2 diabetes, CD36-mediated ER stress and inflammatory signaling (JNK, NF-κB) implicated in diet-induced obesity and reduced insulin sensitivity." (PMID 36410795, 2023). "All three insulin resistance treatments impaired insulin-stimulated GLUT4 translocation in response to 0.5 or 100 nM insulin in wild-type or HA-GLUT4-mRuby3-expressing cells." (PMID 36808134, 2023).